BMP8B (bone morphogenetic protein 8b)
Diseases named in the same sentence as BMP8B in open-access papers (continued):
Sharing a sentence is not in itself a finding about the gene and the disease.
tumor (6 papers, 2013 to 2023). "High BMP8B mRNA expression in the primary tumor was significantly associated with a shorter cancer-specific survival time following a curative resection (P=0.007)." (PMID 24137334, 2013). "It was shown that the expression of BMP8B was significantly increased in tumour compared with normal tissues, while BMP6 and ACVRL1 were expressed at lower levels." (PMID 37333824, 2023). "Upregulation of BMP8B has been demonstrated to diminish cell invasion and tumor growth in pancreatic xenografts." (PMID 32039173, 2019). "The BMP8B gene that encodes a secreted signaling molecule belonging to the TGF-β superfamily was analyzed in the present study, as tumor-derived secreted factors are known to affect the bone marrow, resulting in metastatic progression." (PMID 24137334, 2013). "The tumor samples from the patients were divided into two groups according to the median BMP8B mRNA expression." (PMID 24137334, 2013). "Overlapping BMP6 and BMP8B expression were also evident in the GSE70951 cohort, which includes 47 paired tumours and normal breast tissues." (PMID 37333824, 2023). "Some of the top DNA hypermethylated IRGs, such as BMP8B, PLA2R1, MSX1, DGCR5, and MT1G, were previously identified as tumor suppressors in gastric and other cancers." (PMID 32841292, 2020). "Furthermore, the multivariate analysis revealed that the prognostic power of BMP8B mRNA expression in the tumor was independent of other standard prognostic markers (HR, 2.066; 95% CI, 1.132–3.772; P= 0.018, Table III)." (PMID 24137334, 2013).
cancer (5 papers, 2013 to 2021). A tumor composed of atypical neoplastic, often pleomorphic cells that invade other tissues. "Furthermore, BMP8B has been shown to affect the proliferation and maturation of germ-line cells, while there are few studies of BMP8B expression and effects in cancer." (PMID 31096638, 2019). "This study suggests that BMP8B, a previously unknown secreted factor in cancer progression, has the potential to be used as a prognostic biomarker." (PMID 24137334, 2013). "BMP8B was expressed by the cancer cells in the primary tumors." (PMID 24137334, 2013). "Thus, the results suggest that BMP8B, a previously unknown secreted factor in cancer progression, has the potential to be used as a prognostic biomarker." (PMID 24137334, 2013).
inflammation (1 paper, 2023). Aberrant reaction of the microcirculation characterized by movement of fluid and leukocytes from the blood into extravascular tissues. "The qPCR results indicated that both PACEL and three indole analogues could alleviate DSS-induced intestinal inflammation in mice by inhibiting pro-inflammatory cytokines (MMP7, IL1α) and down-regulating BMP8B expression, thus preventing carcinogenesis of normal colonic epithelial cells." (PMID 37927593, 2023).
BMP8B also shares sentences with these, for which no sentence is quoted: metastatic disease (2 papers); acute coronary syndrome (1); basal cell carcinoma (1); breast tumours (1); cancer of the stomach (1); Crohn disease (1); glioma (1); Hypertension (1); hyperthyroidism (1); Infertility (1); leiomyoma (1); lymphoma (1); metastasis (1); neuroblastoma (1); ulcerative colitis (1).